ABCB1 (ATP binding cassette subfamily B member 1)
Diseases named in the same sentence as ABCB1 in open-access papers (continued):
Sharing a sentence is not in itself a finding about the gene and the disease.
cancer (continued). "The ABCB1 gene is part of a family of ATP-binding cassette (ABC) transporter genes involved in the progression of various types of cancer." (PMID 34702282, 2021). "Our data demonstrated that the intracellular concentration of citarinostat and the HDAC6 inhibiting activity were significantly reduced by ABCB1 and ABCG2, and consequently, cancer cells overexpressing ABCB1 or ABCG2 are insensitive to citarinostat." (PMID 33807514, 2021). "The design of inhibitors of efflux pumps, especially in regard to ABCB1, is a promising strategy in cancer therapy." (PMID 34572790, 2021). "Other studies have shown that some ABC transporters, including ABCA2, ABCA3, ABCB1, and ABCG2, are associated with cancer cell stemness." (PMID 34244494, 2021). "The cause of multidrug resistance (MDR) in cancer is multifaceted, with MDR1 (known as P-glycoprotein, ABCB1) overexpression being the key determinant of HCC drug resistance." (PMID 33723262, 2021). "This positive feedback loop (via upregulation of PTGS2) would further enhance aberrant Wnt signaling in affected cancer tissues, and possibly ABCB1 upregulation." (PMID 35582031, 2021). "Later, several studies with successful knockout of the ABCB1 gene in human carcinoma cell lines have been reported." (PMID 34977876, 2021). "For ABCB1-mediated MDR cancer cells, we used KB-3-1 (parental) and KB-C2 (colchicine-selected ABCB1-mediated MDR cells)." (PMID 33364237, 2020). "More importantly, we discovered an additional mode of action of erdafitinib on modulating the transport function of ABCB1 and resensitizing ABCB1-overexpressing multidrug-resistant cancer cells to conventional chemotherapeutic drugs." (PMID 32466597, 2020). "This study provides evidence that WYE-354 is a substrate of the ABCB1 transporter, implicating that WYE-354 should be avoided for use in ABCB1-mediated MDR cancer." (PMID 32092870, 2020). "Our data showed that the expression of ERRγ was positively correlated with the ABCB1 in liver and breast cancer patients." (PMID 32206097, 2020). "In conclusion, our study provides strong evidence to demonstrate that overexpression of ABCB1 is sufficient to confer cancer cells resistant to GSK-1070916." (PMID 33519482, 2020). "Combining this result with the cytotoxicity profile, it suggested that ABCB1 can pump the drug out of cancer cells, resulting in decreased sensitivity of cancer cells to GSK-1070916." (PMID 33519482, 2020). "On the other hand, ATP-binding cassette sub-family B member 1 (ABCB-1), plays a role in drug-resistance development in several cancers." (PMID 32041631, 2020). "Particularly high ABCB1 promoter methylation levels have been found in intestinal cancers, in more advanced cancers, and in lymph vessel invasion-positive cancers." (PMID 33066132, 2020). "The two ABC transporters most commonly involved with the development of MDR in cancer cells are the ABC transporter subfamily B member 1 (ABCB1/P-gp/MDR1) and the ABC transporter subfamily G member 2 (ABCG2/BCRP/MXR)." (PMID 32098067, 2020). "Mechanistically, ERRγ can mediate the chemoresistance of cancer cells via upregulation of ABCB1 and facilitation of FAO." (PMID 32206097, 2020). "It has been suggested that topotecan resistance in some types of cancers is related to the overexpression and active drug efflux functions of ABCB1 and ABCG2." (PMID 33425914, 2020). "To date, there is still no therapeutic agent approved by the U.S. Food and Drug Administration (FDA) for the modulation of ABCB1 or ABCG2 or treatment for patients with multidrug-resistant cancers." (PMID 31941029, 2020). "Since we performed the assays with human cancer cells, the human ABCB1 model is more suitable for this study." (PMID 32092870, 2020). "In fact, the resistance to paclitaxel and doxorubicin was completely reversed by either 1 or 5 μM of sapitinib, in the HEK293/pcDNA3.1 and cancer cells overexpressing ABCB1 transporter." (PMID 33163405, 2020).
cancer (continued). "ABCB1 confers a multidrug-resistant phenotype in cancers, limiting the absorption and toxicity of chemotherapeutic agents." (PMID 32428872, 2020). "ABCB1 is epigenetically silenced in healthy adult gastric tissue, therefore this expression in cancer was a direct result of oncogenic reprogramming that seemed to be integral to gastric cancer cells’ survival." (PMID 32587767, 2020). "Only in a few cancers is the expression of ABCB1 and/or ABCG2 proteins higher than that found in normal tissues." (PMID 31729540, 2020). "At present, ABCB1 has been the most studied among various transporters because it has been demonstrated as a primary mechanism of resistance in many cancer cells." (PMID 32903706, 2020). "In the present work, the potential chemosensitization effect of erdafitinib on multidrug-resistant cancer cells was assessed in human cell lines overexpressing ABCB1 or ABCG2." (PMID 32466597, 2020). "For example, midostaurin, through inhibition of the drug transport function of the ATP‐binding cassette (ABC) protein ABCB1, resensitizes multidrug‐resistant cancer cells to standard chemotherapeutic agents." (PMID 31967735, 2020). "Since upregulation of ABC-transporters is a common mechanism of cancer drug resistance, we used qRT-PCR to examine the mRNA levels of the most frequently observed transporters, ABCB1, ABCC1 and ABCG2, in our CDK7 inhibitor-resistant cell lines." (PMID 31530935, 2020). "Upregulation of ABCB1 has been reported for a variety of cancer types including lung, colon, kidney, adrenal gland, liver, pancreas, and hematological malignancies." (PMID 33066132, 2020). "We discovered that by reducing the function of ABCB1, erdafitinib significantly resensitized ABCB1-overexpressing multidrug-resistant cancer cells to therapeutic drugs at sub-toxic concentrations." (PMID 32466597, 2020). "Inhibiting ABCB1 by targeting its cancer-specific upstream regulators thus represents a safer approach, mitigating the damage to normal tissue." (PMID 32020017, 2020). "The most intriguing finding was the association of efflux transporters ABCB1 and ABCG2 with favourable OS in cancers." (PMID 33202946, 2020). "In particular, apatinib was able to prevent multidrug resistance (MDR) of cancer cells against other conventional chemotherapeutic drugs by inhibiting ABCB1 and ABCG2-mediated drug export." (PMID 31399906, 2020). "Demethylation of the ABCB1 gene in the cancer cell lines leads to decreased accumulation of the anticancer agent inside the cancer cells and results in acquisition of the MDR phenotype." (PMID 32370233, 2020). "We demonstrated that SNX-2112 inhibited cancer cell proliferation, decreased ABCB1 and ABCG2 gene expression levels and reduced the colony formation capacity of ECSLCs, which was enhanced by STAT3 silencing." (PMID 33390934, 2020). "In this study, we demonstrated that overexpression of ABCB1 can render cancer cells resistant to GSK-1070916." (PMID 33519482, 2020). "Recently reviewed information suggested that an ABCB1 locus including another transporter ABCB4 is frequently amplified in cancer and mainly in tumors or in vitro models with induced drug resistance." (PMID 32872162, 2020). "IPA showed significant changes in the expression levels of genes associated with gastrointestinal disease (Abcb1, Guca2a, Muc2, Rag2, Itga6, and Shh), inflammatory disease (Abcb1, Muc2, and Rag2), and cancer (Muc2, Guca2a, and Rag2)." (PMID 33396408, 2020). "In cancer, ABCB1 actively effluxes a broad range of chemotherapeutic agents from cells leading to multidrug resistance." (PMID 32020017, 2020). "A proposed method to inhibit ABCB1 is to target its cancer-specific, upstream regulators, mitigating damage to normal tissue." (PMID 32020017, 2020). "It was worth noting that the results of the MTT assay showed that the IC50 values of peptides HX-12A, HX-12B, and HX-12C in ABCB1-overexpressing cancer cells (KB-C2) were 6.45 μM, 7.61μM, and 6.06 μM, respectively." (PMID 32903706, 2020).
cancer (continued). "A greater understanding of the cancer-specific regulation of ABCB1 and its role in drug resistance is required to facilitate the design of new therapeutic strategies." (PMID 31770110, 2020). "It has been extensively reported that overexpression of ABCB1 in cancer cells can confer resistance to chemotherapeutic agents such as paclitaxel, vincristine, colchicine, as well as tyrosine kinase inhibitors (TKIs) such as imatinib and dasatinib." (PMID 33519482, 2020). "ABCB1 is an efflux protein pump, which transports toxic endogenous substances, drugs, and xenobiotics out of normal tissues and cancer cells (Hartmann, Kim, & Piquette‐Miller, 2001)." (PMID 32243098, 2020). "ABCB1 (P-glycoprotein) is responsible for multidrug resistance in cancer cells by preventing drugs from reaching the cytosol, thereby leading to failure of chemotherapy treatment." (PMID 32054924, 2020). "In conclusion, we identified a key role of ERRγ in chemoresistance of cancer cells via upregulation of ABCB1 and facilitation of FAO." (PMID 32206097, 2020). "It is important to enhance the effect and bioavailability of chemotherapeutic drugs that are substrates of ABCB1 transporter in ABCB1-overexpression cancer cells and reverse ABCB1-mediated MDR." (PMID 32984343, 2020). "Collectively, we found that m6A-induced ERRγ is essential for chemoresistance of cancer cells through upregulation of ABCB1 and metabolic reprogramming." (PMID 32206097, 2020). "We previously reported that inhibition of oncogenic Ras/MEK increases PpIX accumulation in cancer cells by reducing PpIX efflux through ATP-binding cassette sub-family B member 1 (ABCB1) and ferrochelatase (FECH)-catalysed PpIX conversion to haem." (PMID 33335181, 2020). "Our findings together with these reports strongly argue that ABCB1 has a positive impact on cancer patient survival." (PMID 33202946, 2020). "Most studies investigating DNA methylation of ABC transporters in cancer are limited to ABCB1, ABCC1, and ABCG2, only few studies hint at aberrant DNA methylation of other members of the ABC transporter family." (PMID 33066132, 2020). "The most relevant ABC transporters expressed by brain endothelial cells are P-glycoprotein (P-gp, ABCB1), breast-cancer-related protein (BCRP, ABCG2), and the multiple drug-related proteins (MRP1, -4, -5; ABCC1, -4, -5)." (PMID 33322488, 2020). "In conclusion, this study demonstrates that NVP-CGM097 can reverse the MDR in ABCB1-overexpressing cancer cells through blocking the function of ABCB1 transporter." (PMID 32793491, 2020). "ABCB1 is a P-glycoprotein highly expressed in several different types of human cancer and has been recognized to be a key player in the multidrug resistance phenotype." (PMID 33194754, 2020). "Sorcin is expressed at high levels in many cancers, from many different tissues, usually with MD-resistant phenotype dependent on ABCB1 expression." (PMID 32268494, 2020). "Our results revealed that at sub-toxic concentrations, erdafitinib selectively reverses multidrug resistance mediated by ABCB1 in multidrug-resistant human cancer cell lines." (PMID 32466597, 2020). "We showed a correlation of ABCB1 with favourable OS in four separate cancer types (HNSC, PAAD, SARC, SKCM)." (PMID 33202946, 2020). "To investigate the effects of the three peptides (HX-12A, HX-12B, and HX-12C) on ABCB1 transporter, we first tested the sensitivity of ABCB1-overexpressing cancer cells (KB-C2) to these three peptides." (PMID 32903706, 2020). "ABCB1 serves as a membrane efflux pump that extrude its substrates from the cancer cells, thereby interfering with the therapeutic effect of a diverse range of anticancer drugs." (PMID 33519482, 2020). "In recent decades, the focus of ABCB1 in cancer research has gradually shifted to the development of a therapeutic strategy to overcome ABCB1-mediated MDR." (PMID 33519482, 2020).
cancer (continued). "To this end, we examined the protein expression of ABCB1 in KB-V-1 cancer cells and ABCG2 in S1-M1-80 cancer cells by immunoblotting after treating cells with sitravatinib at various concentrations (100–500 nM) for 72 h as described in Materials and Methods." (PMID 31941029, 2020). "Since we used human cancer cells for the assays, the human ABCB1 model can better illustrate the interaction of WYE-354 and ABCB1 within human cancer cells." (PMID 32092870, 2020). "In our study, the expression of the ABCB1 gene was checked in cancer tissue and in blood samples taken from patients at three points (at the time of diagnosis, 100 days and one year from the surgical intervention)." (PMID 32277145, 2020). "Conclusions: m6A induced ERRγ confers chemoresistance of cancer cells through upregulation of ABCB1 and CPT1B." (PMID 32206097, 2020). "To date, our mechanistic insight into how cancer cells can enhance ABCB1 function is still incomplete." (PMID 32056006, 2020). "Next, we examined the chemosensitizing effect of erdafitinib in multidrug-resistant cancer cells overexpressing ABCB1 or ABCG2." (PMID 32466597, 2020). "In a drug screen on a large cancer cell line panel representing multiple tumour types, a significant correlation between the expression of ABCB1 and response to ICEC0942 was observed across the panel." (PMID 31530935, 2020). "In conclusion, we reveal a potential drug repositioning treatment option for multidrug-resistant cancers by targeting ABCB1 and ABCG2 with sitravatinib and should be further investigated in future clinical trials." (PMID 31941029, 2020). "Tumor uptake of substrate radiotracers, including [99mTc]sestamibi, [18F]fluoropaclitaxel, [11C]verapamil, and (R)-[11C]verapamil, has also been used as a marker of ABCB1 function in drug-resistant cancers." (PMID 31729540, 2020). "One of the mechanisms by which Wnt/β-catenin signaling induces chemoresistance is by up-regulating the expression of P-glycoprotein (P-gp/ABCB1, encoded by the MDR1 gene), increasing the energy-dependent efflux of cytotoxic drugs from cancer cells." (PMID 32727463, 2020). "In patients treated with 5-fluorouracil (5-FU), the ABCB1 transporter was reported to be slightly overexpressed in cancer tissue compared with normal tissue, whereas the ABCB1 transporter was significantly overexpressed in patients treated with irinotecan." (PMID 33163405, 2020). "We found that RN486 significantly increased the efficacy of paclitaxel and doxorubicin in both drug-selected carcinoma cells and transfected cells overexpressing ABCB1." (PMID 32984343, 2020). "The main mechanism by which cancer stem cells protect themselves is through the expression of ATP-binding cassette or ABC transporters (ABCB1/P-glycoprotein/MDR1, ABCC1, ABCG2, etc.)." (PMID 31878027, 2019). "The ability of statins to inhibit ABCB1 transporter has been previously observed in various model systems and in drug-resistant cancer cell lines." (PMID 30813251, 2019). "Previous studies have reported that c-Myc, c-Jun, HIF-1 and CtBP1 can positively modulate ABCB1 expression in cancers, leading to the development of drug resistance." (PMID 31249297, 2019). "Those classical 1,4-dihydropyridines are known to act as inhibitors of the transmembrane efflux pump ABCB1 in cancer cells where they enhance the toxicity of applicated cytostatic agents." (PMID 31398786, 2019). "Results of these studies indicate that selenoesters and selenoanhydrides, previously found as active anticancer or ABCB1 efflux pump inhibitors in cancer cells, also displayed a promising antimicrobial potential against the MDR bacterial strains." (PMID 31014009, 2019). "P-glycoprotein (Pgp/ABCB1) overexpression is associated with multidrug resistance (MDR) phenotype and, consequently, failure in cancer chemotherapy." (PMID 31137684, 2019).
cancer (continued). "Specifically, P-glycoprotein or ABCB1 has an especially important role as an exporter in cancer cells due to its location and its wide spectrum of substrates." (PMID 30909401, 2019). "It is worth noting that Apatinib also reverses the multidrug resistance (MDR) condition in several cancer cell lines by the inhibition of ATP Binding Cassette Subfamily B Member 1 (ABCB1) and ATP-binding cassette superfamily G member 2 (ABCG2)." (PMID 31570733, 2019). "The paucity of representative cell line models that retain a sub-population of ABCB1 expressing cancer stem cells and are amenable to pre-clinical assays has hampered progress towards this goal." (PMID 31311995, 2019). "Incapacitation of anticancer drugs can be triggered by the overexpression of ABCB1, making the therapy for cancer difficult or even fail." (PMID 31801248, 2019). "Efflux transporters such as P-glycoprotein/ABCB1 have been shown to confer multidrug resistance in cancer." (PMID 30863990, 2019). "Among the efflux transporters, P-glycoprotein (P-gp, gene symbol ABCB1) plays an important role in the resistance of cancer cells to a variety of chemotherapeutic treatments." (PMID 31877856, 2019). "Then we investigated reversal effect of FW-04-806 on MDR in ABCB1 or ABCG2 overexpressing cancer cells." (PMID 31472682, 2019). "Various miRNAs such as miR‐9,26 miR‐200c,29 miR‐206,30 and miR‐49531 can regulate the expression of ABCB1 in cancer cells." (PMID 30609256, 2019). "We previously have demonstrated that targeting ABCB1 by CRISPR/Cas9-based genome editing reverses ABCB1-mediated multidrug resistance in cancer cells, resulting in the increase of the sensitivity and intracellular accumulation of the anti-cancer drugs." (PMID 30873379, 2019). "Overexpression of ABCB1 is identified as one of the chief components of cancer chemotherapy failure." (PMID 31921655, 2019). "The expression of efflux transporters such as the ATP-binding cassette (ABC) transporter ABCB1 is an important resistance mechanism in therapy-refractory cancer cells." (PMID 31728254, 2019). "ABCB1 (MDR1/P-gp) was the first eukaryotic ABC transporter identified that confers MDR in cancer cells." (PMID 31472682, 2019). "P-glycoprotein (P-gp/ABCB1) is the most investigated member among the multidrug efflux transporters for inducing drug resistance in various cancers." (PMID 31920517, 2019). "Recently, several studies proposed a new way to spread drug resistance within a cancer cell population, that was intercellular transfer of ABCB1." (PMID 31830995, 2019). "For example, multi-drug resistance protein 1 (MDR1; aka P-glycoprotein and ABCB1) is overexpressed in many malignant neoplasms and its expression can also be induced by chemotherapy." (PMID 31781551, 2019). "In fact, several miRNAs have been reported to have a direct or indirect role in the regulation of the expression or activity of ABCB1 in DR in different cancers." (PMID 35582584, 2019). "Overexpression of drug efflux transport ABCB1 is correlated with multidrug resistance (MDR) among cancer cells." (PMID 31921655, 2019). "Together with FOXO3 activation, FOXO1 overexpression via miRNA interactions is involved in upregulation of ABCB1 gene, coding for P-glycoprotein, well known responsible for decreased drug accumulation in multidrug-resistant cancer cells." (PMID 31234353, 2019). "We reveal that in vitro TMP195 treatment significantly enhances drug-induced apoptosis and sensitizes multidrug-resistant cancer cells overexpressing ABCB1 or ABCG2 to anticancer drugs." (PMID 31905792, 2019). "Multiple mechanisms for the regulation of ABCB1 expression in cancer cell lines have been discussed." (PMID 31248089, 2019). "The ATP-binding cassette transporter G2 (ABCG2; also known as breast cancer resistance protein, BCRP) has been suggested to be involved in clinical multidrug resistance (MDR) in cancer like other ABC transporters such as ABCB1 (P-glycoprotein)." (PMID 30890942, 2019).